YAP1 (Yes1 associated transcriptional regulator)
Diseases named in the same sentence as YAP1 in open-access papers (continued):
Sharing a sentence is not in itself a finding about the gene and the disease.
colorectal tumors (3 papers, 2022 to 2024). "Although these studies established a strong relationship between Yap1 and gp130 cytokine production in the establishment of pancreatic and colorectal tumors, the cellular mechanisms underpinning Yap1-dependent inflammatory processes in cancer remain undefined." (PMID 37957015, 2024). "Under normal conditions, the Hippo–YAP1 signaling axis plays a vital role in cell homeostasis within the colon, whereas YAP1 is up-regulated in colorectal tumors." (PMID 37793774, 2023). "A significant positive correlation was found between ANKHD1 and YAP1 in the tested colorectal tumors: 70% (84 of 120) of tumors with high expression of ANKHD1 also showed high YAP1 levels (bottom)." (PMID 35110552, 2022). "An obvious difference of YAP1 expression was observed between colorectal tumors and normal tissues (P = 0.0069): 39% (13 of 33) of normal colorectal tissue tested high expression of YAP1, whereas 65% (96 of 148) of tumors showed high YAP1expression (top)." (PMID 35110552, 2022). "To further determine the relevance of ANKHD1 and YAP1, we evaluated YAP1 protein expression in colorectal tumors as well as normal tissues by IHC on tissue microarrays." (PMID 35110552, 2022). "The staining of YAP1 was divided into three levels in colorectal tumor tissue: low staining, moderate staining, and strong staining." (PMID 35110552, 2022).
diabetic cardiomyopathy (3 papers, 2020 to 2025). Diabetic cardiomyopathy is a disorder of the heart muscle in people with diabetes. "Our research delineates a regulatory step for ferroptosis activation via DNA‐PKcs‐mediated YAP1 phosphorylation and nuclear retention in diabetic cardiomyopathy." (PMID 40279648, 2025). "Elevated cardiac concentrations of active YAP1 have been demonstrated in mice fed with high-fat diet and in patients with diabetic cardiomyopathy." (PMID 32390875, 2020). "Thus, YAP1 O-GlcNAcylation might be a promising target for the study of diabetic cardiomyopathy." (PMID 32390875, 2020). "Furthermore, the YAP1/TEAD1-OSM feedback cycle develops in the heart of high-fat-diet (HFD)-fed mice following PO, and contributes to the progression of diabetic cardiomyopathy." (PMID 32390875, 2020). "However, the relationship between YAP1 and diabetic cardiomyopathy is not completely clear." (PMID 32390875, 2020).
disc degeneration (3 papers, 2019 to 2024). "Activation of Hippo signaling or knockout of the key gene Yap1 in the cartilage endplate severed the cheese-like morphological change and disc degeneration after lumbar spine instability (LSI) surgery, while blocking the Hippo signaling reversed this process." (PMID 38816384, 2024). "By regulating YAP1 in vivo and in vitro, we can achieve alleviation of ICMT-induced senescence of endplate chondrocytes and effective treatment of disc degeneration." (PMID 36944987, 2023).
dysplasia (3 papers, 2015 to 2024). A usually neoplastic transformation of the cell, associated with altered architectural tissue patterns. "Meanwhile, we detected the co-expression of DAB2 and active-YAP1 in patients with atrophic gastritis, intestinal metaplasia, and dysplasia." (PMID 38481347, 2024). "Positive expression of YAP1 was also detected in 79.2% of GCs, 47.1% of dysplasia cases, and 15.0% of normal gastric tissues." (PMID 26267324, 2015). "This was further confirmed at the protein level for VEGF and YAP1 by immunohistochemistry using an independent cohort of OSCC, dysplasia and epithelial hyperkeratosis." (PMID 36835505, 2023).
hemangioendothelioma (3 papers, 2021 to 2024). A vascular proliferation characterized by the presence of prominent endothelial cells and the formation of vascular channels. "Notably, this variant shows more aggressive clinical behavior than conventional composite hemangioendothelioma and is associated with fusions of the PTBP1::MAML2 or EPC1::PCH2 genes; single cases also harbored YAP1::FOXR1 and ARID1B::MAML2 fusions." (PMID 39264472, 2024). "Moreover, variant WWTR1 and YAP1 gene fusions have been identified in cardiac EHE and subsets of retiform and composite hemangioendotheliomas, respectively." (PMID 40491864, 2024). "Additionally, a frequent fusion of YAP1 with the MAML2 gene has been reported both in conventional composite hemangioendothelioma and in hobnail (retiform) hemangioendothelioma, highlighting the close relationship of these two entities." (PMID 39264472, 2024). "The molecular defects seen in some cases of RH include rearrangements and fusions of YAP1 and MAML2 genes, also seen in cases of composite hemangioendotheliomas." (PMID 33593408, 2021).
hyperandrogenism (3 papers, 2021 to 2024). Excessive secretion of androgens from the adrenal glands or gonads. "Since MIGA2 and YAP1 are associated with hyperandrogenism in PCOS, this study may provide new clues to the molecular pathogenesis of PCOS." (PMID 38012141, 2023). "Similarly, SNPs within YAP1, TOX3 and IRF1/RAD50 were only significant in the lean group, and have previous association with ovulatory dysfunction, hyperandrogenism and increased testosterone levels respectively." (PMID 38408933, 2024). "In addition, YAP1 has been identified as a susceptibility gene for PCOS, and MIGA2 is associated with hyperandrogenism in PCOS." (PMID 38012141, 2023). "Testosterone (T) and estradiol (E2) induce the hyperactivation of YAP1 to stimulate GC proliferation, which may participate in hyperandrogenism-induced oligo-ovulation." (PMID 34881258, 2021).
Insulin resistance (3 papers, 2020 to 2025). Increased resistance towards insulin, that is, diminished effectiveness of insulin in reducing blood glucose levels. "Therefore, the effect of lncARSR/YAP1/IRS2/AKT axis on NAFLD by regulating insulin resistance needs further elaboration." (PMID 32169080, 2020).
Intellectual disability (3 papers, 2017 to 2022). "Although the symptoms of the two brothers rather represent the severe end of the phenotypic spectrum, the overlap confirms an association of YAP1 not only with ocular anomalies, but also with intellectual disability and developmental delay." (PMID 36553572, 2022). "For example, heterozygous LOF mutations of the widely expressed transcriptional co-activator YAP1 cause diverse defects in patients, such as ocular abnormalities or craniofacial/intellectual disabilities, suggesting that the observed phenotypes are the result of tissue-specific HIs of YAP1." (PMID 33433399, 2020).
keratoconus (3 papers, 2022 to 2024). A degenerative, structural disorder of the eye, characterized by a cone-shaped protrusion of the cornea. "We also detected the up-regulation of the mechano-transducer YES-associated protein 1 (YAP1) as well as its cooperator TEA domain transcription factor (TEAD1) in keratoconus stromal cells." (PMID 35821117, 2022). "Importantly, the authors identified cathepsin D (CTSD), cathepsin K (CTSK), YES-associated protein 1 (YAP1), and TEA domain transcription factor (TEAD1) as novel biomarkers in keratoconus stromal cells." (PMID 37138096, 2023). "Remarkably, we detected significantly elevated YAP1 and TEAD1 in keratoconus stromal cells." (PMID 35821117, 2022).
laryngeal carcinoma (3 papers, 2022 to 2024). Carcinoma that arises from the laryngeal epithelium. "High expression of YAP1, TEAD4, and TP73 was significantly associated with high grade, advanced stage, supraglottic location of tumors, nodal metastases, and recurrence of human laryngeal cancer." (PMID 36479120, 2022). "In laryngeal cancer, PRMT5 promotes EMT through YAP1 signaling." (PMID 38444414, 2024).
lentivirus infection (3 papers, 2016 to 2022). Virus diseases caused by the Lentivirus genus. "To test the function of Yap1 in breast TICs, we introduced active Yap1 with a S127A mutation into TICs using lentivirus infection (lentivirus-Yap1)." (PMID 26695440, 2016). "To explore the potential role of YAP1, we overexpressed YAP1 in MV4-11 cells and MOLM13 cells by lentivirus infection." (PMID 35656547, 2022). "To confer the function of YAP1 in GC cells, we generated YAP1-knockdown SGC-7901 and MKN-28 cell lines using two YAP1-specific shRNAs by lentivirus infection and control cells infected by the lentivirus containing a scramble shRNA." (PMID 31175271, 2019).
macular degeneration (3 papers, 2021 to 2024). Loss of vision in the central portion of the retina (macula), secondary to retinal degeneration. "Next, we aimed to assess if the combination of Verteporfin (YAP1 inhibitor commonly used for macular degeneration) with Sonidegib in DAOY and UW228 may provide a synergic effect." (PMID 34944872, 2021). "VPF is a clinically approved photosensitizer for treating macular degeneration and has been found to disrupt the YAP1-TEAD interaction, thus inhibiting YAP1 signaling." (PMID 39624057, 2024). "Verteporfin (Visudyne), a photosensitizer approved for macular degeneration treatment, was the first molecule developed and was shown to inhibit YAP1/TEAD interactions, diminishing YAP1 signaling." (PMID 38893092, 2024).
malignant glioma (3 papers, 2017 to 2022). A grade III or grade IV glioma arising from the central nervous system. "Malignant glioma is associated with a high expression of YAP1." (PMID 35054765, 2022). "NF2 expression is significantly reduced in malignant gliomas and normally functions to inhibit YAP1 by promoting LATS activation and YAP1 degradation." (PMID 34012965, 2021). "So we assumed that IKBKE promoted malignant glioma growth and EMT via enhancing the expression of YAP1 and TEAD2." (PMID 28548934, 2017). "We also testified that YAP1 and TEAD2 promoted epithelial–mesenchymal transition (EMT) in malignant glioma." (PMID 28548934, 2017).
non-alcoholic fatty liver disease (3 papers, 2020 to 2024). "RA significantly mitigates non-alcoholic fatty liver disease (NAFLD) by repairing mitochondrial damage and modulating the YAP1/TAZ-PPARγ/PGC-1α signaling pathway." (PMID 39459158, 2024).
rectal cancer (3 papers, 2020 to 2024). A primary or metastatic malignant neoplasm that affects the rectum. "lncRNA GAS5 interacts with YAP1 phosphorylation and degradation to inhibit rectal cancer progression." (PMID 36299503, 2022). "Furthermore, Morrbid promotes EMT in rectal cancer via Hippo/YAP1 by upregulating YAP1 expression." (PMID 39263145, 2024).
serous ovarian carcinoma (3 papers, 2017 to 2024). "By analyzing protein expression and quantifying nuclear versus cytoplasmic levels of YAP1 protein in 21 matched primary high-grade serous ovarian carcinomas and metastatic nodules, we found that primary tumors showed cytoplasmic YAP1 protein expression in almost 50% of tumor cells." (PMID 28827520, 2017). "Human papillomavirus (HPV) and hyperactivated YAP1 form a YAP1-HPV oncogenic alliance to drive the malignant transformation of fallopian tube epithelial cells and the initiation of high grade serous ovarian carcinoma (HGSOC)." (PMID 39271776, 2024). "We performed the qRT-PCR analysis of TGFβ components (TGFB1, TGFB2, TGFBR1, TGFBR2), Wnt5A/ROR1/ROR2, and Hippo-related genes (YAP1, TAZ, CCN1, and CCN2) in serous ovarian cancer subtypes (LGSOC, HGSOC, BLSOC) compared to the normal ovary." (PMID 35053353, 2022).
soft tissue tumors (3 papers, 2019 to 2024). "Strikingly, YAP1 overexpression was much higher in the soft tissue neoplasms, suggesting activation of the Hippo pathway in these tumors, as YAP is the effector of the Hippo pathway in association with TAZ/TEAD transcription factors." (PMID 35978432, 2022).
synovial sarcoma (3 papers, 2019 to 2024). "In addition, mutual activation of the nuclear YAP1/TAZ-TEAD and b-catenin-TCF pathways in SS was demonstrated to interact with SS18-SSX, which is crucial for the interdependence of YAP1 and b-catenin in synovial sarcoma." (PMID 39451213, 2024).
tongue squamous cell carcinoma (3 papers, 2021 to 2022). A squamous cell carcinoma that arises from the tongue. "Dasatinib, an Src family kinase inhibitor, suppressed the initiation of YAP1-induced tongue squamous cell carcinoma in a mouse model." (PMID 36294681, 2022).
vascular tumor (3 papers, 2025). "Multivariate analysis identified COPB2 combined with YAP1 expression, vascular tumor thrombus, and TNM staging as independent risk factors." (PMID 40191726, 2025). "Additionally, gene fusions involving FOS, FOSB, YAP1, and WWTR1 have been discovered in vascular tumors, improving diagnostic accuracy." (PMID 40428263, 2025).
acral melanoma (2 papers, 2022). "The other 19 acral melanomas, including two melanomas in situ and 17 invasive melanomas, showed YAP1 expression." (PMID 36428972, 2022). "Subsets of acral melanoma patients harbour amplifications of PAK1 (22% of tumours) and YAP1 (12% of tumours) loci, suggesting a dependency on these pathways for proliferation and/or invasion." (PMID 35159327, 2022).
adrenocortical tumors (2 papers, 2016 to 2023). "YAP1 is a potential target of the Wnt/beta-catenin pathway, which plays an important role in adrenocortical tumors (ACT)." (PMID 27705928, 2016).
age-related macular degeneration (2 papers, 2019 to 2021). Age-related loss of vision in the central portion of the retina (macula), secondary to retinal degeneration. "Verteporfin (VP) is a suppressor of the YAP1-TEAD complex, also known as an FDA-approved drug used as a photosensitizer for photodynamic therapy in patients with age-related macular degeneration." (PMID 34722240, 2021).
anaplastic ependymoma (2 papers, 2015 to 2018). Anaplastic ependymoma is a rare, malignant type of ependymoma that most often arises in the supratentorial region of the brain of children and young adults and that manifests with variable symptoms including headaches, nausea, vision impairment, memory loss and difficulty walking. "Recent genomic analyses have indicated that most supratentorial anaplastic ependymomas are associated with fusion events involving RELA or YAP1." (PMID 29440180, 2018). "YAP1 also displayed nuclear staining, most prominent in anaplastic ependymoma cases (not shown)." (PMID 25775275, 2015).
atrophic gastritis (2 papers, 2019 to 2024). "We detected YAP1 expression levels in 28 human atrophic gastritis (AG) samples and 13 GC samples by quantitative real‐time PCR (qPCR), revealing obviously higher YAP1 expression in GC tissues compared to that in AG tissues." (PMID 31145543, 2019).
Azoospermia (2 papers, 2024 to 2025). Absence of any measurable level of sperm,whereby spermatozoa cannot be observed even after centrifugation of the semen pellet. "In this study, we are the first to report that the expression level of YAP1 was lower in NOA testicular tissues compared to obstructive azoospermia (OA) patients with normal spermatogenesis, and notably, there was relevance between single-nucleotide variants (SNVs) of YAP1 and the risk of NOA." (PMID 39659446, 2024). "Importantly, YAP1 abnormalities were found to be associated with non-obstructive azoospermia (NOA) as manifested as lower expression level of YAP1 in testicular tissues of NOA patients and YAP1 single-nucleotide variants (SNVs) in 777 NOA patients." (PMID 39659446, 2024). "Abnormalities in the molecular pathway synergistically regulated by RAD21 and YAP1 can directly lead to impaired spermatogenesis, which provides a new direction in the mechanistic resolution of non-obstructive azoospermia." (PMID 40642059, 2025).
B-cell lymphoma (2 papers, 2021 to 2025). "In this study in B-cell lymphomas, we also found the low mutation frequencies of the major components of Hippo pathway like LATS1 (1%), LATS2 (1%), YAP1 (1%), and FAT1 (6%)." (PMID 34926267, 2021).
bacterial pneumonia (2 papers, 2019 to 2025). Acute infection of the lung parenchyma caused by bacteria (e.g., Streptococcus pneumoniae, Haemophilus influenzae, Chlamydia pneumoniae, Mycoplasma pneumoniae, and Legionella pneumophila). "The absence of Yap/Taz in mice affects the repair and regeneration of alveolar epithelial cells in bacterial pneumonia, while downregulation of YAP1 alleviates LPS-induced lung injury by promoting M2 macrophage polarization." (PMID 40636259, 2025). "Importantly, recent analysis of murine lung bacterial pneumonia has revealed the importance of YAP1/TAZ in controlling the dynamic NFκB injury response, required to allow alveolar regeneration." (PMID 31323030, 2019).
carcinoids (2 papers, 2022 to 2025). "The most notable difference was seen in carcinoid tumors, where the tumors in the Alcala cohort had significantly fewer YAP1 + cases compared to the carcinoid tumors in the Rousseaux cohort despite retaining similar NE signature characteristics." (PMID 40586102, 2025).
Cerebral ischemia (2 papers, 2022 to 2024). Restriction of arterial blood supply to the brain associated with insufficient oxygenation to support the metabolic requirements of the tissue. "The mitochondrial function in Yap1 knockout mice is impaired, whereas Yap1 can reduce nerve inflammation and inhibit microglial cell activation after acute cerebral ischemia reperfusion injury." (PMID 39400418, 2024). "Furthermore, Yap1 could influence astrocyte‐driven microglial activation and negatively regulate neuroinflammation in the nervous system to prevent astrogliosis and affect microglial activation in acute cerebral ischemia–reperfusion injury." (PMID 39400418, 2024).
cholestasis (2 papers, 2020 to 2025). Impairment of the bile flow caused by obstruction within the liver, or outside the liver in the bile duct system. "YAP1 activation was previously recognized as an important role to promote liver regeneration and alleviate liver injury in cholestasis by two studies." (PMID 32296329, 2020). "In conclusion, our findings proved that calcipotriol suppressed the NLRP3 signal by activating YAP1 to alleviate liver injury and retard fibrogenesis in cholestasis." (PMID 32296329, 2020). "Meantime we found that calcipotriol supplement could work to inhibit NLRP3 inflammasome activation in cholestasis through counteracting the extreme downregulation of YAP1 to alleviate live injury and fibrosis." (PMID 32296329, 2020). "Our in vivo study revealed that the protein levels of YAP1 in liver tissue decreased markedly in cholestasis, which may possibly be ascribed to the effect of FXR, the major nuclear receptor involved in BA metabolism." (PMID 32296329, 2020). "Calcipotriol may work to counteract metabolic inflammation via activating VDR and overexpession of YAP1 to suppress the excessive activation of NLRP3 inflammasome in cholestasis." (PMID 32296329, 2020). "Our study identifies SALL4 as a crucial regulator in YAP1-mediated HC-to-CCA malignant transformation and regenerative HC-to-CC conversion in a cholestasis model." (PMID 40932240, 2025). "Our research combined with previous studies proved that VDR and YAP1 was extremely downregulated in cholestasis and both VDR–/– mice and YAP1–/– mice were more sensitive to cholestasis-induced liver injury." (PMID 32296329, 2020). "Calcipotriol supplement revised the YAP1 downregulation in cholestasis but did not effect the expression of VDR." (PMID 32296329, 2020).
Cirrhosis (2 papers, 2020 to 2021). A chronic disorder of the liver in which liver tissue becomes scarred and is partially replaced by regenerative nodules and fibrotic tissue resulting in loss of liver function. "This highlights that YAP1 rs11225163 might be associated with cirrhosis in NASH-HCC." (PMID 32283835, 2020).
coronary artery disease (2 papers, 2022). "Overall, YAP1 orchestrates opposing roles in fibrotic changes after ischemic heart disease: increased survival and contractile function in cardiomyocytes, and clonal expansion and the acceleration of fibrosis in cardiac fibroblasts." (PMID 36015285, 2022).